PPARGC1A (PPARG coactivator 1 alpha)
Description:
Transcriptional coactivator for steroid receptors and nuclear receptors. Greatly increases the transcriptional activity of PPARG and thyroid hormone receptor on the uncoupling protein promoter. Can regulate key mitochondrial genes that contribute to the program of adaptive thermogenesis. Plays an essential role in metabolic reprogramming in response to dietary availability through coordination of the expression of a wide array of genes involved in glucose and fatty acid metabolism. Acts as a key regulator of gluconeogenesis: stimulates hepatic gluconeogenesis by increasing the expression of gluconeogenic enzymes, and acting together with FOXO1 to promote the fasting gluconeogenic program. Induces the expression of PERM1 in the skeletal muscle in an ESRRA-dependent manner. Also involved in the integration of the circadian rhythms and energy metabolism (By similarity). Required for oscillatory expression of clock genes, such as BMAL1 and NR1D1, through the coactivation of RORA and RORC, and metabolic genes, such as PDK4 and PEPCK (By similarity).
Synonyms: LEM6; PGC1; PGC1A; PPARGC1; PGC-1alpha; PPARAGCIα; PGC-1(alpha); PGC-1v
Tractability: Small molecule: a structure with a bound ligand is known; a high-quality ligand is known. PROTAC: UniProt records ubiquitination sites on it; ubiquitination databases record sites on it.
Gene: Protein-coding gene on chromosome 4 (23,755,041 to 23,904,089, reverse strand). Ensembl gene ENSG00000109819.
Subcellular location: Nucleus (Isoform 1); Nucleus, PML body; Nucleus (Isoform B4); Cytoplasm (Isoform B4-8a); Nucleus; Nucleus (Isoform B5); Nucleus (Isoform 9)
Subcellular location (Human Protein Atlas): Nucleoplasm; Cytosol
Pathways (Reactome):
Developmental Biology: Regulation of MITF-M dependent genes involved in metabolism; Transcriptional regulation of brown and beige adipocyte differentiation by EBF2; Transcriptional regulation of white adipocyte differentiation
Gene expression (Transcription): FOXO-mediated transcription of oxidative stress, metabolic and neuronal genes; MLL4 and MLL3 complexes regulate expression of PPARG target genes in adipogenesis and hepatic steatosis; Regulation of RUNX2 expression and activity
Circadian clock: Expression of BMAL (ARNTL), CLOCK, and NPAS2; RORA,B,C and NR1D1 (REV-ERBA) regulate gene expression
Organelle biogenesis and maintenance: Activation of PPARGC1A (PGC-1alpha) by phosphorylation; Transcriptional activation of mitochondrial biogenesis
Cellular responses to stimuli: Heme signaling
Metabolism: PPARA activates gene expression
Metabolism of proteins: SUMOylation of transcription cofactors
Gene Ontology:
Molecular function: nuclear receptor binding; protein binding; sequence-specific DNA binding; transcription coactivator activity; ubiquitin protein ligase binding; chromatin DNA binding; DNA binding; DNA-binding transcription factor binding; RNA binding; RNA polymerase II-specific DNA-binding transcription factor binding; transcription coregulator activity; lncRNA binding; nucleic acid binding
Biological process: gluconeogenesis; mitochondrion organization; negative regulation of smooth muscle cell proliferation; positive regulation of DNA-templated transcription; positive regulation of gene expression; positive regulation of gluconeogenesis; positive regulation of transcription by RNA polymerase II; regulation of DNA-templated transcription; brown fat cell differentiation; cellular respiration; cellular response to oxidative stress; circadian regulation of gene expression; digestion; energy homeostasis; fatty acid oxidation; intracellular glucose homeostasis; mRNA processing; negative regulation of neuron apoptotic process; positive regulation of cold-induced thermogenesis; positive regulation of fatty acid oxidation; protein stabilization; protein-containing complex assembly; regulation of circadian rhythm; respiratory electron transport chain; response to muscle activity; and 7 more
Cellular component: cytoplasm; cytosol; nucleoplasm; nucleus; chromatin; PML body
Genetic constraint (gnomAD): Loss-of-function variants: 24 observed, 88.72 expected, observed/expected ratio (o/e) 0.27, 90% interval 0.19 to 0.38. The upper end of that interval is the gene's LOEUF score, 0.38, which puts it in group 1 of 6, group 1 being the genes least tolerant of losing a copy. Missense variants: 876 observed, 1,008.3 expected, observed/expected ratio (o/e) 0.87, 90% interval 0.82 to 0.92. Synonymous variants: 363 observed, 372.06 expected, observed/expected ratio (o/e) 0.98, 90% interval 0.89 to 1.06.
Homologues: Orthologues: chimpanzee PPARGC1A (99% identical), macaque PPARGC1A (99% identical), guinea pig PPARGC1A (96% identical), dog PPARGC1A (95% identical), pig PPARGC1A (95% identical), rabbit PPARGC1A (95% identical), mouse Ppargc1a (94% identical), rat Ppargc1a (93% identical), tropical clawed frog ppargc1a (77% identical), zebrafish ppargc1a (58% identical), Drosophila melanogaster srl (19% identical). Paralogues in human: PPARGC1B (32% identical), PPRC1 (26% identical).
Diseases named in the same sentence as PPARGC1A in open-access papers:
PPARGC1A is named in the same sentence as 486 diseases in open-access papers, as found by Europe PMC text mining. Sharing a sentence is not in itself a finding about the gene and the disease. The quoted sentences say what the papers report.
Obesity (458 papers, 2006 to 2026). Accumulation of substantial excess body fat. "PPARGC1A is associated with cholesterol metabolism, obesity, and age-related diseases such as Parkinson’s disease." (PMID 40417629, 2025). "The peroxisome proliferator-activated receptor gamma coactivator 1 alpha (PPARGC1A) has been associated with obesity and related metabolic disorders, affecting adipocyte differentiation and lipid metabolism." (PMID 38028584, 2023). "Several epidemiological studies have linked PPARGC1A variation at rs8192678 with obesity and other cardiometabolic diseases." (PMID 37171500, 2023). "Carriers of the T allele of rs2970847 had decreased performance of PPARGC1A and higher risk for obesity." (PMID 36587194, 2022). "PPARGC1A rs2970847 is a synonymous variant, which is reported associated with the risk of type 2 diabetes, obesity, and insulin resistance." (PMID 36587194, 2022). "The PPARGC1A gene rs8192678 polymorphism has been previously related to the development of obesity, biochemical parameters such as glucose, insulin, triglycerides and inflammatory markers, resting energy expenditure, and physical fitness level." (PMID 35936915, 2022). "Initially, the importance of PPARGC1A gene diversity in the context of obesity development was confirmed in genome-wide association studies." (PMID 36558537, 2022). "A total of 24 osteoporosis-related genes, including IGF1, IL6, pyruvate dehydrogenase kinase 4 (PDK4), PPARGC1A, and TF, were also associated with obesity and diabetes." (PMID 35328013, 2022). "The 482Ser allele is associated with a decrease in the expression level of the PPARGC1A gene, a decrease in oxidative processes and mitochondrial biogenesis, and obesity in men leading an inactive lifestyle." (PMID 36140844, 2022). "A polymorphism in the PPARGC1A gene is related to obesity and type 2 diabetes, while the down-regulation of PCSK1N gene expression is also associated with obesity." (PMID 32485856, 2020). "In human GWAS analysis a single nucleotide variant of Ppargc1a (rs8192678) has been associated with susceptibility to obesity and insulin resistance." (PMID 33143653, 2020). "Peroxisome proliferator-activated receptor gamma coactivator-1 (PPARGC1A; PGC-1α) is a transcriptional co-regulator, and its polymorphisms are proposed as obesity metabolic regulators and to be involved in epithelial–mesenchymal transition." (PMID 31493764, 2019). "Expression of PPARGC1A has been reported to be associated with metabolic factors, such as type 2 diabetes, hypertension, obesity." (PMID 18588668, 2008). "A frequent substitution of a glycine to serine amino acid at residue 482 in human PPARGC1A was described in 2001, and has been demonstrated to be associated with diabetes, hypertension, and obesity." (PMID 19077249, 2008). "Assessing UCP1 and thermogenic gene products (e.g., MyoD1, LHX8, DIO2, PPARGC1A) in tissue materials removed during elective surgery may be used to predict obesity risk and initiate interventions to mitigate further adipose tissue expansion at an early stage." (PMID 38069028, 2023). "The GLy482Ser (rs8192678) SNP is a variant in the protein coding sequence of PPARGC1A, whose deleterious effect has been related to obesity, as well as its associated complications, which include CHD, T2DM, non-alcoholic fatty liver disease (NAFLD), and arterial hypertension." (PMID 36466447, 2022). "Hence, our results showed that individuals with the PPARGC1A rs8192678 (T) genotype have a higher risk of developing obesity and metabolic disorders such as insulin resistance, according to previous data." (PMID 35936915, 2022). "Low PCSK1 expression might be related to obesity and diabetes, and PPARGC1A expression can increase obesity risk." (PMID 35328013, 2022).
Obesity (continued). "Furthermore, we found that expression of Ppargc1a mRNA, recently linked to inhibition/modulation of obesity induced hepatic inflammation, was higher in TKO-HFD mice than in TWT-HFD mice, suggesting a mechanism for lack of hepatic inflammation in TKO-HFD mice." (PMID 26168159, 2015). "A good example is the peroxisome proliferator-activated receptor gamma coactivator1α (PPARGC1A) Gly482Ser polymorphism, in which the 482Ser allele is associated with increased risk of obesity and type 2 diabetes, whereas the ‘favourable’ Gly482 allele is associated with elite athletic performance." (PMID 23573268, 2013). "The PPARGC1A Gly482Ser polymorphism is also associated with obesity, hypertension, and diabetes." (PMID 18588668, 2008). "The Gly482Ser polymorphism in peroxisome proliferator-activated receptor gamma coactivator-1 alpha (PPARGC1A) has been demonstrated to be associated with diabetes, obesity and hypertension, all of which are important risk factors for left ventricular diastolic dysfunction." (PMID 19077249, 2008). "While the direct influence of Ppargc1a on Ep300 has not been previously reported, the relationship from Ep300 to Ppargc1a is well-documented, where Ep300 acts as a co-activator, particularly in obesity and thermogenesis." (PMID 40924721, 2025). "Concurrently, TRF intervention reversed the obesity-induced downregulation of peroxisome proliferator-activated receptor alpha (Ppara) and its coactivator Ppargc1a, which are crucial for activating genes involved in fatty acid catabolism." (PMID 39519077, 2024). "The results of skyline query analysis showed that EP300, PPARG, and PPARGC1A were dominant and, therefore, have potential as targets for treating obesity." (PMID 39208245, 2024). "High blood sugar can change the methylation status of the PPARGC1A gene too, which can lead to obesity and brown adipose tissue problems in the long run." (PMID 38254965, 2024). "Integration analysis using a skyline query revealed three main targets, EP300, PPARG, and PPARGC1A, which are potential targets for fighting obesity." (PMID 39208245, 2024). "The results showed that BS21 treatment dramatically upregulated the mRNA expression of SIRT1 (Sirt1), PGC-1α (Ppargc1a), and FNDC5/irisin (Fndc5), due to increased muscle weight loss by obesity." (PMID 35276805, 2022). "UAL treatment also increased the expression of Ppara, which encodes a protein that improves insulin resistance, ameliorates obesity, and cooperates with PPARGC1A to control lipid oxidation and thermogenesis in the brown adipose tissue." (PMID 33920841, 2021). "We also sought to determine if the AGE/RAGE/DIAPH1 axis is linked to markers of adipogenesis (PPARG & PPARGC1A) and metabolic genes that we previously identified to be regulated by RAGE in a mouse model of obesity (UCP1 and CIDEA)." (PMID 34103691, 2021). "We also observed an increased transcription of Ppargc1a and Tfeb genes in the inguinal white adipose tissue of a mouse model of diet-induced obesity." (PMID 34992716, 2021). "PPARGC1A can also be involved in blood pressure control, regulation of cellular cholesterol homeostasis, and the development of obesity." (PMID 34828287, 2021). "The single nucleotide variation of the PPARGC1A gene rs8192678 is correlated to susceptibility to T2DM, the relative risk of obesity and insulin resistance, and lower β-cell function index." (PMID 33817136, 2019). "Established VDR target genes such as PPARD and PPARGC1A, which are involved in protection against an adverse metabolic phenotype (obesity, insulin resistance), were positively correlated with serum 25OHD3 in this study." (PMID 28199350, 2017). "Given that FGF21 signaling has also been linked to modulation of Ppargc1a activity, miR-34a is likely to negatively regulate the expression of browning genes in obesity through suppression of Ppargc1a transcriptional activity." (PMID 28878735, 2017).
Obesity (continued). "We also showed for the first time that PPARGC1α DNA methylation levels in placenta likely contribute to mediate the relationship between maternal glycemia and cord blood leptin levels, which could explain why these newborns have an increased risk of obesity and T2D later in life." (PMID 27340502, 2016). "The aim of this study was to investigate the relationship between functional polymorphisms Gly482Ser in PPARGC1A and Pro12Ala in PPARG2 with the presence of obesity and metabolic risk factors." (PMID 26185753, 2015). "NAFLD is often accompanied by obesity, hypertriglyceridemia, type 2 diabetes, and insulin resistance, and PPARGC1A knockout mice develop hepatic steatosis." (PMID 18588668, 2008). "In humans, PPARGC1A has been thoroughly investigated because of its presumed role in the obesity pandemic and correlated diseases like type II diabetes mellitus and cardiovascular complications, especially in search of possible future therapies." (PMID 17026777, 2006). "PPARGC1A can be induced by cold and exercise, it has been proven to function as a natural protection against obesity in brown fat of mice by producing heat and it is especially expressed in tissues with a high energy demand, like muscle and brown fat." (PMID 17026777, 2006). "PPI analysis revealed MTNR1B’s strong association with diabetes, obesity, cancer, and circadian rhythm disorders, collectively known as circadian syndrome, and MTNR1B’s close interaction with thermogenic genes (UCP1, PPARG, and PPARGC1A)." (PMID 40697662, 2025). "A common polymorphism in PPARGC1A (rs8192678, C/T, Gly482Ser) has been associated with obesity and related metabolic disorders, but no published functional studies have investigated direct allele-specific effects in adipocyte biology." (PMID 37171500, 2023). "Thus, obesity leads, at least in part, to the onset of AD by compromising mitochondrial function, while PPARGC1α and COQ3 play key roles in this process." (PMID 36568118, 2022). "Downregulation of PPARGC1α impairs mitochondrial biogenesis and oxidative metabolism in obesity." (PMID 36568118, 2022). "The results of this study suggest that polymorphisms of the MC4R, PPARGC1A, MSRA, and TFAP2B genes may be associated with obesity-related traits in a sample of Portuguese children." (PMID 36499740, 2022). "Other studies have reported a lack of association between PPARGC1A Gly482Ser polymorphism and obesity or a decreased metabolic risk for those with 482Gly/Gly genotype." (PMID 36466447, 2022). "Furthermore, long-term supplementation with Pt reduced body weight gain and increased transcription levels of Ppargc1a and Tfeb in a mouse model of diet-induced obesity." (PMID 34992716, 2021). "The results of this study elucidate the role of Gly482Ser polymorphism in PPARGC1A and may provide useful information for the design of PPARGC1A variant-based therapeutic strategies against CAD, NAFLD, T2DM, obesity, hypertension, and metabolic diseases." (PMID 34394332, 2021). "Overall, these studies report that adherence to a Mediterranean Diet and/or calorie restriction were associated with decreased DNA methylation in obesity-related genes such as PDK4, KCNQ1, WT1, SH2B1, FTO, BDNF, and PPARGC1A or inflammatory genes such as TNF-α." (PMID 31506096, 2019). "Recent investigations have indicated that single nucleotide polymorphisms (SNPs) of the PPARGC1A gene may be associated with the susceptibility and progression of NAFLD, obesity, type 2 diabetes mellitus, and hypertension in various ethnicities." (PMID 31390852, 2019). "The predictive value of PPARGC1α DNA methylation variations will have to be established, but our results provide some additional evidence in support of the fetal epigenetic metabolic programming of obesity." (PMID 27340502, 2016).